RN7SL612P (RNA, 7SL, cytoplasmic 612, pseudogene)
Gene: Miscellaneous RNA gene on chromosome 1 (156,985,755 to 156,986,049, reverse strand). Ensembl gene ENSG00000266160.
Homologues: Orthologues: chimpanzee Metazoa_SRP (99% identical), macaque Metazoa_SRP (96% identical). Paralogues in human: RN7SL2 (84% identical), RN7SL1 (84% identical), RN7SL126P (84% identical), RN7SL3 (82% identical), RN7SL448P (82% identical), RN7SL45P (81% identical), RN7SL769P (81% identical), RN7SL11P (81% identical), RN7SL577P (81% identical), RN7SL7P (81% identical), RN7SL408P (80% identical), RN7SL357P (80% identical), and 704 more.